GCNT1 (glucosaminyl (N-acetyl) transferase 1)
Description:
Glycosyltransferase that catalyzes the transfer of an N-acetylglucosamine (GlcNAc) moiety in beta1-6 linkage from UDP-GlcNAc onto mucin-type core 1 O-glycan to form the branched mucin-type core 2 O-glycan. The catalysis is metal ion-independent and occurs with inversion of the anomeric configuration of sugar donor (By similarity). Selectively involved in synthesis of mucin-type core 2 O-glycans that serve as scaffolds for the display of selectin ligand sialyl Lewis X epitope by myeloid cells, with an impact on homeostasis and recruitment to inflammatory sites (By similarity). Can also act on glycolipid substrates. Transfers GlcNAc moiety to GalGb4Cer globosides in a reaction step to the synthesis of stage-specific embryonic antigen 1 (SSEA-1) determinant (By similarity). Can use Galbeta1-3GalNAcalpha1- and Galbeta1-3GalNAcbeta1-oligosaccharide derivatives as acceptor substrates (By similarity).
Synonyms: C2GlcNAcT; C2GNT; C2GnT-L; NACGT2; NAGCT2; C2GNT1; G6NT
Tractability: Antibody: UniProt predicts a signal peptide or a membrane-spanning region.
Target class: Enzyme; Transferase
Gene: Protein-coding gene on chromosome 9 (76,419,850 to 76,651,203, forward strand). Ensembl gene ENSG00000187210.
Subcellular location: Golgi apparatus membrane
Subcellular location (Human Protein Atlas): Nuclear speckles
Pathways (Reactome):
Metabolism of proteins: O-linked glycosylation of mucins
Gene Ontology:
Molecular function: beta-1,3-galactosyl-O-glycosyl-glycoprotein beta-1,6-N-acetylglucosaminyltransferase activity; protein binding; glycosyltransferase activity; UDP-glycosyltransferase activity
Biological process: cell adhesion molecule production; glycoprotein biosynthetic process; leukocyte tethering or rolling; protein O-linked glycosylation via N-acetyl-galactosamine; positive regulation of leukocyte tethering or rolling
Cellular component: Golgi cisterna; Golgi membrane; nuclear speck; trans-Golgi network; membrane
Genetic constraint (gnomAD): Loss-of-function variants: 17 observed, 30.82 expected, observed/expected ratio (o/e) 0.55, 90% interval 0.38 to 0.83. The upper end of that interval is the gene's LOEUF score, 0.83, which puts it in group 3 of 6, group 1 being the genes least tolerant of losing a copy. Missense variants: 474 observed, 550.42 expected, observed/expected ratio (o/e) 0.86, 90% interval 0.8 to 0.93. Synonymous variants: 176 observed, 197.98 expected, observed/expected ratio (o/e) 0.89, 90% interval 0.79 to 1.01.
Homologues: Orthologues: chimpanzee GCNT1 (99% identical), macaque GCNT1 (98% identical), dog GCNT1 (88% identical), mouse Gcnt1 (85% identical), guinea pig GCNT1 (85% identical), pig GCNT1 (85% identical), rat Gcnt1 (84% identical), rabbit GCNT1 (76% identical), tropical clawed frog gcnt1 (62% identical), Caenorhabditis elegans gly-16 (25% identical), Caenorhabditis elegans gly-15 (25% identical), Caenorhabditis elegans gly-17 (24% identical), and 16 more. Paralogues in human: GCNT3 (51% identical), GCNT4 (40% identical), GCNT2 (34% identical), GCNT7 (25% identical), XYLT1 (24% identical), XYLT2 (22% identical), WSCD2 (11% identical), WSCD1 (10% identical).
Diseases named in the same sentence as GCNT1 in open-access papers:
GCNT1 is named in the same sentence as 45 diseases in open-access papers, as found by Europe PMC text mining. Sharing a sentence is not in itself a finding about the gene and the disease. The quoted sentences say what the papers report.
prostate carcinoma (20 papers, 2011 to 2025). A carcinoma that arises from epithelial cells of the prostate gland. "Here, we show that GCNT1, which encodes a key glycosyltransferase enzyme controlling O-glycan branching, is upregulated in aggressive prostate cancer tissue." (PMID 37813880, 2023). "Increased GCNT1 expression has been linked to prostate cancer progression and is a predictor of recurrence after radical prostatectomy." (PMID 34359624, 2021). "ST6GalNAc1 is frequently upregulated concurrently with another important glycosylation enzyme GCNT1 previously associated with prostate cancer progression and implicated in Sialyl Lewis X antigen synthesis." (PMID 26452038, 2015). "Besides prostate cancer, gene GCNT1 has previously been linked to neural phenotypes, including the cranial width and cognitive measurements." (PMID 32915819, 2020). "High GCNT1 expression was shown to be associated with altered O-glycosylation in prostate cancer." (PMID 32752173, 2020). "UAP1 and GCNT1 have been shown to be upregulated in PCa, and the amino-sugar conjugate, O-linked N-acetylglucosamine (O-GlcNAc) is significantly elevated in prostate cancer tissue." (PMID 26452038, 2015). "Notably, overexpression of GCNT1 has been reported to be associated with progression of prostate cancer." (PMID 24753245, 2014). "However, the impact of GCNT1 on the global glycosylation of prostate cancer cells and the molecular mechanisms underlying the role GCNT1 in prostate cancer are largely unknown." (PMID 37813880, 2023). "The effect of GCNT1 levels on prostate cancer cell adhesion was also investigated using cell adhesion assays." (PMID 37813880, 2023). "Together, these findings reveal GCNT1 overexpression can alter oncogenic gene expression pathways in prostate cancer that are important in disease progression." (PMID 37813880, 2023). "Our in vitro studies show knockdown of GCNT1 suppresses prostate cancer cell proliferation and colony formation, whereas overexpression of GCNT1 had the opposite effect." (PMID 37813880, 2023). "Consistent with previously published studies, the findings reported here also correlate GCNT1 gene expression levels with more aggressive prostate cancer and show upregulation of GCNT1 increases the growth of prostate tumours." (PMID 37813880, 2023). "The glycosyltransferase GCNT1 has been previously identified as upregulated in prostate cancer and correlates with aggressive disease at both the gene and protein level." (PMID 37813880, 2023). "Using in vitro and in vivo models, we show GCNT1 promotes the growth of prostate tumours and can modify the glycome of prostate cancer cells, including upregulation of core 2 O-glycans and modifying the O-glycosylation of secreted glycoproteins." (PMID 37813880, 2023). "Taken together, these studies provide insights into how upregulation of GCNT1 can modify the prostate cancer glycome, however additional studies will be needed to further identify and characterise the polypeptide substrates of GCNT1." (PMID 37813880, 2023). "Our findings reveal GCNT1 can alter the glycome of prostate cancer cells, specifically by upregulating the expression of core 2 O-glycan structures (including the cancer-associated glycan SLeX) and modifying the O-glycosylation of secreted glycoproteins." (PMID 37813880, 2023). "Next, we analysed GCNT1 gene expression in primary prostate cancer tissue samples from the TCGA PRAD clinical cohort (n = 493), and identified tumours with high (n = 124) and low (n = 123) GCNT1 expression." (PMID 37813880, 2023). "Next, we monitored GCNT1 gene levels in a molecular subgroup of prostate cancer patients with metastatic potential at presentation (previously published by33,34)." (PMID 37813880, 2023). "We next investigated the impact of GCNT1 expression on the biology of prostate cancer cells using both in vitro and in vivo assays." (PMID 37813880, 2023).
prostate carcinoma (continued). "Next, we analysed the O-glycoproteome in secretomes of DU145 prostate cancer cells with upregulated GCNT1 using mass spectrometry." (PMID 37813880, 2023). "Here, we analyse four independent cohorts of patient RNA samples and further confirm upregulation of GCNT1 gene expression in aggressive prostate cancer." (PMID 37813880, 2023). "Our study highlights the role of GCNT1 in aggressive prostate cancer and provides novel insights into the role of aberrant glycosylation in disease pathology." (PMID 37813880, 2023). "To further investigate the role of GCNT1 in prostate cancer cells, we used RNA-sequencing to search for gene expression pathways that change with upregulation of GCNT1." (PMID 37813880, 2023). "Using site specific O-glycoproteomics, we identified 60 potential substrates for GCNT1 in the prostate cancer secretome." (PMID 37813880, 2023). "This identified 60 glycopeptides as potential substrates for GCNT1 in prostate cancer cells, including a potential increase in core 2 O-glycan structures on PSAP and MUC16." (PMID 37813880, 2023). "Using quantitative PCR, we further show the GCNT1 gene is 1.8-fold upregulated in prostate cancer tissue relative to benign prostate hyperplasia in an additional patient cohort (n = 20, p = 0.0248)." (PMID 37813880, 2023). "GCNT1, regulated by eca-miR-143, is induced by androgens in prostate cancer (PC) cells at the protein level, and the production of GCNT1 is important for the synthesis of cancer-associated O-glycans and contributes to PC cell viability." (PMID 36553607, 2022). "FUT1 and one of GCNT1, GCNT2 or GCNT 3 are essential enzymes for F77-specific O-linked glycosylation in prostate cancer cells." (PMID 29423071, 2018). "The expression of GCNT1 has strong correlation with tumorigenicity, development and metastasis in human prostate cancers." (PMID 27768594, 2016). "Our data are also the first to suggest a link between the AR and expression of GCNT1 in prostate cancer." (PMID 27428423, 2016). "Here, we show for the first time that expression of both GCNT1 and the SLeX antigen are regulated by androgens in prostate cancer cells." (PMID 27428423, 2016). "Furthermore, we find that upregulation of GCNT1 can alter the glycome of prostate cancer cells to increase levels of core 2 O-glycans and upregulate expression of sLeX, and can impact oncogenic gene expression patterns." (PMID 37813880, 2023). "Together, these experiments suggest that GCNT1 may impact the phenotype of prostate cancer cells by modifying both cell surface glycosylation and the O-glycosylation of proteins secreted by prostate cancer cells." (PMID 37813880, 2023). "Furthermore, using RNA sequencing, we find upregulation of GCNT1 in prostate cancer cells can alter oncogenic gene expression pathways important in tumour growth and metastasis." (PMID 37813880, 2023). "It is interesting to speculate that the role of GCNT1 in prostate cancer tumour growth and control of gene expression patterns could be due to some of its protein substrates’ roles or combined functions." (PMID 37813880, 2023). "Here, we monitor GCNT1 gene expression in four additional prostate cancer clinical cohorts." (PMID 37813880, 2023). "Here, we show that GCNT1, an enzyme that plays an essential role in the formation of core 2 branched O-glycans and is crucial to the final definition of O-glycan structure, is upregulated in aggressive prostate cancer." (PMID 37813880, 2023). "Taken together, our findings reveal potential mechanisms to explain how upregulation of GCNT1 might contribute to the prostate cancer pathology, however further studies will be needed to further unpick the mechanisms involved." (PMID 37813880, 2023). "The observed association of GCNT1 expression with CLL prognosis is incongruent with data reported for solid tumors (e.g., bladder and prostate cancers), in which high expression of GCNT1 was associated with poor prognosis, presumably through the protection of tumors from NK cells." (PMID 35711441, 2022).
prostate carcinoma (continued). "Expression of both GCNT1 and the sLex antigen is controlled by androgens in prostate cancer cells." (PMID 34359624, 2021). "The results of our study indicate that GCNT1 and its interacting factors may function via fatty acid related pathways, which promote the development of prostate cancer among people who intake higher amount of omega-6 fatty acids." (PMID 32915819, 2020). "Notably, high expression of the GCNT1 has been previously reported in multiple cancers, including in prostate cancer." (PMID 32915819, 2020). "Two other genes that were found in this study to interact in association with GCNT1 are SCN2B and SCN4B, components of voltage-gated sodium channels, and both of these factors have been previously associated with the developing prostate cancer and promoting cancer metastasis." (PMID 32915819, 2020). "In recent study, a gene expression array showed GCNT1 was overexpressed in prostate cancer tissue." (PMID 26390303, 2015). "Our findings confirm upregulation of GCNT1 gene levels in prostate cancer tissue compared to normal or benign prostate tissue, and suggest GCNT1 may be upregulated in patients with increased risk of metastasis and those developing relapse to castrate resistant disease." (PMID 37813880, 2023). "For O-glycosylation in prostate cancer, GCNT1 (sometimes C2GNT1) glycosyltransferase plays an essential role in the formation of core 2 branched O-glycans, promoting chain-branching and elongation." (PMID 39594740, 2024). "Of 31 reciprocally-regulated glycosylation enzymes, a set of 8 (GALNT7, ST6GalNAc1, GCNT1, UAP1, PGM3, CSGALNACT1, ST6GAL1 and EDEM3) were significantly up-regulated in clinical prostate carcinoma." (PMID 27428423, 2016). "In this study we confirm androgen regulation of ST6GalNAc1 and show for the first time a link between androgens and two additional O-glycosylation enzymes in prostate cancer, GALNT7 and GCNT1." (PMID 27428423, 2016). "Through the analysis of seven datasets (TCGA, GSE30521, GSE4602, GSE55945, GSE69223 GSE104131, and GSE200879), we identified two upregulated genes (AMACR and GCNT1) and seven downregulated genes (TGFB3, SRD5A2, PGM5, HOXD10, AOX1, HSPB6, and SNAI2) in prostate cancer compared to normal tissue." (PMID 38374143, 2024). "Validation at the protein level confirmed that upregulation of GCNT1 in prostate cancer cells promotes loss of Galectin-1 and analysis of The Cancer Genome Atlas Prostate Adenocarcinoma (TCGA PRAD) cohort revealed a correlation between the GCNT1 and LGALS1 genes in clinical prostate cancer tissue." (PMID 37813880, 2023). "Within this dataset, GCNT1 is 2.6-fold upregulated in the ‘metastatic subgroup’ compared to the ‘non-metastatic’ sub-group, suggesting upregulation of the GCNT1 gene in primary prostate cancer patients presenting with metastatic biology (n = 20, p = 0.0494)." (PMID 37813880, 2023).
breast carcinoma (4 papers, 2014 to 2025). "Partial overlap in staining was observed in breast cancer and normal spleen tissues, although anti-GCNT1 showed broader staining." (PMID 40681527, 2025). "Indeed up-regulation of GCNT1 has been reported in many cancer types, including endometrial carcinoma, breast cancer, bladder cancer, testicular germ cell tumor, and colorectal and pulmonary carcinoma." (PMID 24753245, 2014).
lung carcinoma (4 papers, 2011 to 2023). "Previously, it was reported that GCNT1 expression is associated with the metastatic potential of colorectal cancer, lung cancer, testicular cancer and PCa." (PMID 26390303, 2015).
pancreatic cancer (4 papers, 2020 to 2025). "To select suitable pancreatic cancer cells for the assay, we analyzed the expression of genes B3GNT6 (encoding β3Gn-T6) and MUC5AC, together with genes encoding core 2 synthases (GCNT1, GCNT3, and GCNT4) by qRT-PCR." (PMID 33253272, 2020).
colorectal cancer (3 papers, 2009 to 2020). A primary or metastatic malignant neoplasm that affects the colon or rectum. "A previous study analyzed GCNT1 mRNA expression in fresh colorectal tumor samples and showed that expression of core 2-branched O-glycans is closely correlated with the malignant potential of colorectal cancer." (PMID 26390303, 2015).
leukemia (2 papers, 2011 to 2023). A malignant (clonal) hematologic disorder, involving hematopoietic stem cells and characterized by the presence of primitive or atypical myeloid or lymphoid cells in the bone marrow and the blood. "We stably knocked down GCNT1 in THP-1 cells, a leukemia cell line that is frequently used as a cell line model for human monocytes and macrophages." (PMID 38141764, 2023).
prostate adenocarcinoma (2 papers, 2023 to 2025). "Analysis of RNA sequencing data from The Cancer Genome Atlas Prostate Adenocarcinoma (TCGA PRAD) cohort reveals GCNT1 gene expression levels are 2.3-fold higher in prostate tumours relative to normal prostate tissue (n = 544, p = 0.021)." (PMID 37813880, 2023).
prostate tumour (2 papers, 2016 to 2023). "In line with previous reports, our study shows that increased expression of GCNT1 promotes the growth of prostate tumours, and building on these findings we also reveal GCNT1 can increase cell adhesion." (PMID 37813880, 2023). "Using both in vitro and in vivo studies, we show that GCNT1 promotes the growth of prostate tumours and regulates oncogenic gene expression pathways that are important for disease progression." (PMID 37813880, 2023).
allergic disease (1 paper, 2023). An immune response that occurs following re-exposure to an innocuous antigen, and that requires the presence of existing antibodies against that antigen. "The identification of GCNT1 as a causal gene for IgE concentration, asthma, and allergic diseases provides additional support for our hypothesis that IgE-associated gene expression changes impact IgE regulation and play a role in multiple IgE-related diseases." (PMID 36793728, 2023). "Given its myriad of roles in the regulation of the immune response, GCNT1 is a particularly attractive potential drug target given that in addition to its putatively causal relation to IgE levels it also was causal for asthma and allergic diseases." (PMID 36793728, 2023). "GCNT1 (beta=1.5, p=0.01)—which is a top result in the MR analysis of expression in relation to asthma and allergic diseases—plays a role in regulating T helper type 1 cell homing, lymphocyte trafficking, and B cell differentiation." (PMID 36793728, 2023).
Alzheimer disease (1 paper, 2020). A progressive, neurodegenerative disease characterized by loss of function and death of nerve cells in several areas of the brain leading to loss of cognitive function such as memory and language. "ASTN2, another gene which interacts with GCNT1, also has demonstrated associations with neural phenotypes including attention-deficit/hyperactivity disorder (ADHD), autism spectrum disorders (ASD), neuronal development, and Alzheimer's disease." (PMID 32915819, 2020).
bronchopneumonia (1 paper, 2020). Acute inflammation of the walls of the terminal bronchioles that spreads into the peribronchial alveoli and alveolar ducts. "The histopathological features observed during infection with low doses of Mtb were recapitulated and exacerbated for those with high doses, with infected Gcnt1-/- mice presenting extensive lung pathology, particularly extensive necrosis, and histological features of bronchopneumonia." (PMID 32203062, 2020).
myocardial hypertrophy (1 paper, 2014). "Finally, it has been shown recently that Gcnt1 up-regulation is associated with myocardial hypertrophy in mice, which supports our theory." (PMID 25051993, 2014).
prostate (1 paper, 2023). "On the other hand, in PRAD, upregulation of the expression of glucosaminyl (N-acetyl) transferase 1 (GCNT1) leads to aberrant expression of SLex on MUC1, but whether this aberrant O-glycosylation is involved in prostate carcinogenesis has not been clearly stated." (PMID 37894512, 2023).
testicular cancer (1 paper, 2015). A primary or metastatic malignant neoplasm that affects the testis. "In immunohistochemistry using a polyclonal antibody, we demonstrated that GCNT1 expression is closely related with the aggressive potential of PCa, testicular cancer, and bladder cancer." (PMID 26390303, 2015).
tuberculosis (1 paper, 2020). A chronic, recurrent infection caused by the bacterium Mycobacterium tuberculosis. "Our findings reveal a previously unappreciated link between Gcnt1, neutrophilia and susceptibility to M. tuberculosis infection, uncovering new players balancing the immune response in tuberculosis." (PMID 32203062, 2020).